TRIM3 (tripartite motif containing 3)
Diseases named in the same sentence as TRIM3 in open-access papers (continued):
Sharing a sentence is not in itself a finding about the gene and the disease.
tumor (33 papers, 2009 to 2026). "57% have a loss of 11p, including the tumor suppressor TRIM3, which also showed reduced expression in the same samples." (PMID 30367051, 2018). "In order to investigate this possibility, we targeted four equidistant regions of the TRIM3 gene, including the two areas of possible homozygous loss in the three primary tumor samples ASIII 098, GBM 157 and GBM 164 by quantitative real-time PCR (Q-PCR)." (PMID 19250537, 2009). "Our team discovered TRIM3 as a tumor-associated gene in CRC by high-content screening techniques." (PMID 36894560, 2023). "Several genes are contained within this interval that might be involved in brain development and/or tumor suppression, including TRIM3 and a cluster of genes encoding the more distantly related TRIM5, TRIM6, TRIM22, and TRIM34 genes." (PMID 19250537, 2009). "The tumor suppressive function of TRIM3 in GBM may be linked to its regulation of p21." (PMID 30031392, 2018). "We found that TRIM3 overexpression significantly attenuated tumor growth, but TLR3 knockout reversed this effect." (PMID 41545343, 2026). "TRIM3 mRNA expression progressively decreased with increasing tumor stage and N stage in LUAD and LUSC." (PMID 41545343, 2026). "Our murine studies demonstrated sustained tumor suppression via the TRIM3/TLR3 axis over a 15-day period." (PMID 41545343, 2026). "In future studies, the functional mechanisms through which TRIM3-induced IFN-β affects tumor immune cells remain to be fully elucidated." (PMID 41545343, 2026). "Overall, the TRIM3/TLR3 axis suppressed NSCLC progression by directly inhibiting tumor cell proliferation and modulating the infiltration levels of immune cells via IFN-β secretion." (PMID 41545343, 2026). "Recent years have witnessed notable progress in research aimed at unraveling the antitumor mechanism of TRIM3, with far-reaching implications for practical tumor diagnosis, treatment protocols, efficacy evaluation, economics, and pharmaceutical utilization." (PMID 38411731, 2024). "Intriguingly, the deletion of this region is correlated with various cancer types, hinting at a potential tumor-suppressive role of TRIM3." (PMID 38411731, 2024). "The in-depth exploration of the relationship between TRIM3 and tumor development can provide a basis for the formulation of more scientific and rational treatment guidelines." (PMID 38411731, 2024). "By gaining a deeper understanding of the relationship between TRIM3 and tumor development, drug use strategies applicable to patients with different types of tumors can be more precisely determined." (PMID 38411731, 2024). "Examining the expression levels of TRIM3 in different types of tumors can assist physicians in determining the type and grade of the tumor and predicting the prognosis of the patient." (PMID 38411731, 2024). "Several studies have shown decreased expression levels of TRIM3 and identified its potential role as a tumor suppressor in quite a few human cancers." (PMID 35392925, 2022).
tumor (continued). "Since TRIM3 has been shown to have a role as a tumor suppressor in GBM, we focused our investigation on the function of TRIM56 in the development of GBM." (PMID 36471347, 2022). "Previous studies have elucidated that TRIM21, TRIM26, TRIM35, TRIM50, and TRIM56 acted as tumor suppressors by inhibiting tumor cell proliferation, and TRIM3, TRIM16, TRIM21, TRIM25, and TRIM26 negatively regulated migration and invasion in HCC cells." (PMID 35142083, 2022). "To establish the role of TRIM3 as a tumor suppressor in vivo, we used the TRIM3 overexpressing MGC-803 cells to establish xenograft and peritoneal metastasis models in nude mice." (PMID 30031392, 2018). "The number of metastatic tumor nodes in TRIM3 siRNA group was obviously more than that in the vector group (P < 0.05)." (PMID 30031392, 2018). "The tumor weight and volume were increased in the TRIM3 siRNA transfected MGC-803 group (P < 0.01, P < 0.05)." (PMID 30031392, 2018). "The number of metastatic tumor nodes in 50 μg TRIM3-overexpressing exosomes treated group was obviously less than in the vector group (P < 0.05)." (PMID 30031392, 2018). "The number of metastatic tumor nodes in TRIM3 overexpression group was obviously less than that in the vector group (P < 0.01)." (PMID 30031392, 2018). "In consistent with the in vitro results, the tumor weight and volume were decreased in the TRIM3 transfected MGC-803 group (P < 0.01, P < 0.05)." (PMID 30031392, 2018). "In vivo experiment results confirmed that TRIM3 overexpression suppressed tumor growth and metastasis." (PMID 28950898, 2017). "The mean tumor volumes in mice injected with TRIM3-overexpressing cells were significantly smaller than those in mice injected with LV-NC-infecting cells (746 mm3 vs. 2128 mm3 for HepG2; 308 mm3 vs. 1286 mm3 for Bel-7402; both P < 0.001)." (PMID 28950898, 2017). "The mouse model experiment further showed that TRIM3 overexpression significantly inhibited tumor growth and lung metastasis." (PMID 28950898, 2017). "In order to refine somatic deletion mapping and to delimit the minimal area of loss in more detail, we used single nucleotide polymorphic (SNP) markers located within the TRIM3 genomic area to further investigate a selection of tumor samples." (PMID 19250537, 2009). "TRIM3 is located within the loss of allelic heterozygosity (LOH) hotspot of chromosome segment 11p15.5, indicating a potential role in tumor suppression." (PMID 19250537, 2009). "In ASIII 098, tumor genomic dosage in TRIM3 intron 1, at the site between SNP markers rs11605881 and rs11607224 indicated DNA levels below haploidy of ΔCt = -1.98 ± 0.40 (for calculation details)." (PMID 19250537, 2009). "Furthermore, TRIM3 expression correlated positively with the numbers of tumor-infiltrating CD4+ T cells, macrophages, and NK cells in LUAD and LUSC, suggesting that TRIM3 plays a role in promoting immune cell recruitment to the tumor microenvironment." (PMID 41545343, 2026). "Collectively, these data suggest that TRIM3 plays a tumor-suppressive role in NSCLC progression." (PMID 41545343, 2026). "Moreover, TRIM3 overexpression effectively suppresses angiogenesis, resulting in decreased tumor blood supply and growth." (PMID 38411731, 2024). "Research suggests that the loss of heterozygosity on chromosome segment 11p15.5 in malignant gliomas may indicate TRIM3 as a potential candidate tumor suppressor gene for brain tumors." (PMID 38411731, 2024). "Tripartite motif-containing 3 (TRIM3) is a key regulator of tumor cell development." (PMID 38333593, 2024). "In my opinion, first of all, TRIM3 is important in tumor diagnosis." (PMID 38411731, 2024). "This makes it a challenge for us to use TRIM3 molecules to intervene in tumor development." (PMID 38411731, 2024). "The role of TRIM3 in antitumorigenesis and tumor development." (PMID 38411731, 2024).
tumor (continued). "The upregulation of TRIM3 inhibits tumor cell behaviors, including proliferation and metastasis." (PMID 35066729, 2023). "However, the expression of TRIM3 from TCGA or Oncomine database displayed discrepant characters between tumor suppressor and promoting tumor, preferred toward tumor suppressor." (PMID 36894560, 2023). "Next, we investigated the role of TRIM3 in tumor growth in xenograft mouse models." (PMID 35392925, 2022). "The positive rate of TRIM3 was much lower in tumor tissues than adjacent control tissues." (PMID 30031392, 2018). "TRIM3 overexpression in HepG2 and Bel-7402 cells significantly delayed tumor growth in mice." (PMID 28950898, 2017). "Then, we examined TRIM3 expression in the tumor samples with Western blotting." (PMID 28950898, 2017). "The effect of TRIM3 on tumor growth and metastases in nude mice was also investigated." (PMID 28950898, 2017). "The role of TRIM3 in inhibiting tumor growth was also observed in vivo." (PMID 28950898, 2017). "Notably, the TRIM3/TLR3 axis overrides this feedback inhibition through TRIM3-mediated K63-linked ubiquitination of TLR3 at K808, thereby suppressing NSCLC cell proliferation and inhibiting tumor growth." (PMID 41545343, 2026). "Further studies reported that TRIM3 could function as a tumor suppressor in several cancers." (PMID 33292295, 2020). "Furthermore, in vivo tumor growth and lung metastasis were repressed when TRIM3 was overexpressed." (PMID 28950898, 2017). "Both in vitro and in vivo experiments revealed that IFN-β secretion driven by the TRIM3/TLR3 axis suppressed NSCLC cell proliferation and tumor growth." (PMID 41545343, 2026). "To investigate the role of TRIM3 in NSCLC progression, we first analyzed its mRNA levels in patients with LUAD and LUSC across tumor stages and lymph node metastasis status (N stage)." (PMID 41545343, 2026). "Brat in Drosophila brains, and TRIM3 in GBM cells, supress MYC expression, and MYC inhibition reduces both brat tumour growth and GSC tumourigenic potential in vitro and when xenotransplanted in mice." (PMID 38225354, 2024). "One such example is tripartite motif-containing 3 (TRIM3), a member of the TRIM protein family categorized within the RING-type E3 ubiquitin ligase subfamilies, known for its tumor-suppressive role in multiple cancers." (PMID 39719600, 2024). "TRIM3 (class VII) is the natural place to start this section, having originally been identified as BRAin Tumor (BRAT) in Drosophila melanogaster." (PMID 38115822, 2023). "The tumor weight (P < 0.05) and volume (P < 0.05) in mice injected with MGC-803 cells pre-treated with 50 μg TRIM3-overexpressing exosomes were significantly lower than that in controls." (PMID 30031392, 2018). "TRIM3, TRIM16 and TRIM26 down-regulation contributes to poor prognosis in patients with HCC, suggesting the tumor suppressor function in HCC." (PMID 29898761, 2018). "Our findings revealed a reciprocal negative feedback loop in the regulation of IFN-β signaling, highlighting the role of the TRIM3/TLR3 axis in the suppression of NSCLC progression and offering a promising strategy to suppress tumor growth and enhance immunotherapy efficacy in NSCLC." (PMID 41545343, 2026). "TRIM3, a RING domain-containing E3 ubiquitin ligase initially characterized for its ability to regulate intracellular trafficking, has recently been shown to have tumor-suppressive effects across multiple cancers." (PMID 41545343, 2026). "Furthermore, TRIM3’s binding affinity with p21 WAF1/CIP1 impedes its nuclear accumulation, effectively inhibiting tumor growth by impeding the promotion of cyclin D1-CDK4 in the cell cycle." (PMID 38411731, 2024).
tumor (continued). "Furthermore, we compared chemosensitivity to oxaliplatin of tumor xenograft in RKO and SW480 cells with TRIM3 overexpression (Fig. 5c1)." (PMID 36894560, 2023). "SPDEF, TRIM3, HSPB1, SPINT1, EPN3, and LRFN2 were significantly highly expressed in the HER2-positive type than in TNBC (p < 0.05), as the HER2-positive type is reported to have a larger tumor size and higher stage." (PMID 36428562, 2022). "Further clinical and pathological factors including TNM stage, tumor size, and necrosis were used to evaluate TRIM3 gene expression, none of which showed a significant difference between different states of each experimental group." (PMID 36180926, 2022). "In our previous study, we found that TRIM3 expression was significantly down-regulated in most HCC tumor tissues, compared with corresponding noncancerous tissues." (PMID 28950898, 2017). "However, when exposed to tumor antigens for a long time, the expression of tumor suppressors such as PD-1, CTLA4, TIGIT, TRIM3, and LAG3 in the microenvironment will be significantly upregulated, which will lead to impaired killing function and exhaustion of CD8+ T cells." (PMID 36422531, 2022). "However, since all tumor samples obtained were either stage II or III, the levels of TRIM3 gene expression in stage I and IV remain unclear." (PMID 36180926, 2022).
cancer (22 papers, 2009 to 2026). A tumor composed of atypical neoplastic, often pleomorphic cells that invade other tissues. "The comprehensive exploration of TRIM3 is anticipated to pave the way for future advancements in antitumor therapy, which is expected to be a new hallmark for cancer detection and a novel target for drug action." (PMID 38411731, 2024). "The TRIM3 expression log fold change (responders vs. non-responders to FOLFOX) −1.36 in all stages of cancer samples suggesting that the smaller amount of TRIM3 leads to more growth and proliferation which can make the cancer more susceptible to FOLFOX." (PMID 38304289, 2023). "This review primarily focuses on the current state of research regarding the antitumor mechanisms of TRIM3 in different cancers." (PMID 38411731, 2024). "Recent studies have further illuminated TRIM3’s involvement in key signaling pathways during cancer progression." (PMID 38411731, 2024). "Targeted TRIM3 therapy has certain possibilities and has become one of the research hotspots in the field of cancer therapy." (PMID 38411731, 2024). "This review provides a comprehensive examination of the physiological function of TRIM3, focusing on its participation in antitumorigenesis and cancer development." (PMID 38411731, 2024). "TRIM3 is poised to become a significant milestone in cancer detection and a promising focal point for drug intervention." (PMID 38411731, 2024). "Next, the relationship between the expression of the TRIM3 gene and the clinical and pathological status of cancer tissues was evaluated." (PMID 36180926, 2022). "This interesting finding not only increases the understanding of ER alpha posttranslational modifications but also implies the multiple functions of TRIM3 in different cancer backgrounds." (PMID 35392925, 2022). "According to our results, the mean fold change of TRIM3 gene expression in cancer tissues was ~ 0.45, which suggests a ~ 65% reduction in cancer tissues compared to the normal ones." (PMID 36180926, 2022). "Statistical analysis revealed that the expression of TRIM3 correlated closely with cancer recurrence of patients under tamoxifen treatment." (PMID 34508066, 2021). "The human TRIM3 gene is localized at chromosome 11p15.5, a region that has been found to contain numerous cancer-related genes among multiple cancers." (PMID 28950898, 2017). "Similarly, TRIM3 is reported to inactivate the highly cancer-related p38 pathway, thus, enacting its role opposite cancer." (PMID 36180926, 2022). "The human TRIM3 gene maps to chromosome 11p15.5, a region containing numerous cancer-related genes." (PMID 35004288, 2021). "At present, there are few studies about the role of TRIM3 in cancer." (PMID 30031392, 2018). "Tripartite motif containing 3 (TRIM3), a highly conserved E3 ubiquitin ligase within the TRIM protein family, has garnered increasing attention in cancer research." (PMID 41545343, 2026). "TRIM3 and TRIM16 are two important members of the TRIM family, both of which have shown inhibitory effects in different types of cancer, however a few studies have reported oncogenic activities for them." (PMID 36180926, 2022). "According to our results, the expression of TRIM3 and TRIM16 genes in the cancer group undergoes a significant reduction to 0.45 and 0.29 fold, respectively." (PMID 36180926, 2022). "For example, exosomal Tripartite motif-containing 3 (TRIM3) and long non-coding RNA ZFAS1 of GC cells can promote growth and metastasis of cancer cells through mediating stem factors and EMT markers in-vitro and in-vivo." (PMID 34268118, 2021). "TRIM3 and TRIM16 have shown suppressive activity in different cancers." (PMID 36180926, 2022).
cancer (continued). "Regardless, both DUSP4 and TRIM3 on opposite sides of our 9-gene ratio are suppressors of metastasis of hepatic cancer, suggesting tissue-specific if not pan-cancer roles in survival." (PMID 34007962, 2021). "In recent years, many research studies have shown that TRIM family proteins, such as TRIM3, TRIM11, TRIM19, TRIM31, TRIM44 and TRIM59 have been demonstrated to serve a significant role in the tumorigenesis and progression of numerous cancer types." (PMID 30484263, 2019).
infection (2 papers, 2017 to 2023). The state of being infected such as from the introduction of a foreign agent such as serum, vaccine, antigenic substance or organism. "Transwell assay results showed that overexpression of TRIM3 in HepG2 and Bel-7402 cells led to approximately 50% reduction in the numbers of migrated and invaded cells compared with infection of LV-NC (all P < 0.01)." (PMID 28950898, 2017). "TRIM3 was overexpressed in HepG2 and Bel-7402 cells with LV-TRIM3 infection, which further reduced proliferation, colony formation, migration, and invasion of both cell lines." (PMID 28950898, 2017).
TRIM3 also shares sentences with these, for which no sentence is quoted: esophageal squamous cell carcinoma (2 papers); Obesity (2); acute kidney injury (1); diffuse astrocytoma (1); malignant glioma (1); metastatic colorectal cancer (1); prostate carcinoma (1); rectal cancer (1); squamous cell carcinoma (1); T-cell acute lymphoblastic leukemia (1).